ANGPT1 (angiopoietin 1)
Diseases named in the same sentence as ANGPT1 in open-access papers (continued):
Sharing a sentence is not in itself a finding about the gene and the disease.
tumor (continued). "A distinctive expression profile of VEGFA, EFNB2, PECAM1/CD31, ANGPT1 and ANGPT2 was revealed: VEGFA, EFNB2, and ANGPT2 were found overexpressed in 84 % to 95 % of tumour samples." (PMID 26044849, 2015). "Neutrophils, particularly those polarized toward the N2 phenotype, are key contributors to tumor angiogenesis through the secretion of multiple pro-angiogenic factors, including FGF2, VEGF-A, ANGPT1, CXCL8, HGF, and MMP9, which collectively facilitate tumor vascularization and metastatic spread." (PMID 40564191, 2025). "Upon tumor-induced activation, they serve as major transporters of VEGF, which triggers the release of von Willebrand factor (vWF) and subsequent secretion of PDGF, TGF-β, and angiopoietin-1 (ANGPT-1)." (PMID 41383620, 2025). "Furthermore, nanoformulationshave been proposed to efficiently control relevant pro-angiogenicpathways such as VEGF, Tie2/Angiopoietin-1, HIF-1α/HIF-2α,and TGF-β, providing powerful approaches to block tumor growthand metastasis." (PMID 40184281, 2025). "Our previous and present data indicate that ANGPT1 and ANGPT2 might be reciprocally regulated during tumor oxygenation but upregulated together in the refractory period." (PMID 38619734, 2024). "Angiopoietin 1 and its receptor Tie-2 are also found in PRAD cells and their capillaries, which could induce tumor angiogenesis." (PMID 37788005, 2023). "Angiopoietin-1 treatment had no significant influence on tumor volume compared to untreated control tumors on day six." (PMID 37221619, 2023). "Likewise, the actions of angiopoietin 1 and 2, NOTCH and WNT signalling also stimulate tumour angiogenesis." (PMID 35954497, 2022). "Rarely, co‐expression of ANGPT1 and ANGPT2 was observed in few tumor cells." (PMID 35266635, 2022). "In PCa, intraductal grown tumor cells express angiopoietin-1 but not angiopoietin-2 while in the blood vessels close to the ducts, apical tumor cells express angiopoietin-1 and Tie-2." (PMID 33841508, 2021). "This undesirable outcome may be attributed to the ability of tumours to acquire resistance to VEGF inhibition, e.g., by the release of more proangiogenic factors, such as angiopoietin 1 (ANGPT1), resulting in increased amounts of vascular progenitor cells." (PMID 32481570, 2020). "Mechanistically, the HPC-maintaining capacity of the bone marrow was significantly impaired in tumor-bearing mice, with lower expression of HPC maintaining genes (i.e., CXCL12, SCF, ANGPT1, and VCAM1), and reduced levels of mesenchymal stem cells and CXCL12-producing cells." (PMID 33603745, 2020). "Many studies aim to block the binding of ANGPT1/ANGPT2 to TIE-2, thereby, inhibiting tumour growth." (PMID 31217905, 2019). "Tumor-induced lymphangiogenensis is mediated by lymphangiogenic factors, such as vascular endothelial growth factors (VEGFs), fibroblast growth factor (FGF), angiopoietin-1 and angiopoietin-2, and platelet-derived growth factors (PDGFs)." (PMID 29976150, 2018). "In accordance with the result of CD31 staining, the ANGPT1 expression level was obviously increased in MCT-treated mice compared with vehicle, while co-treatment with nafamostat reversed the promoting effect of MCT on tumor growth." (PMID 27240355, 2016). "The same may be occurring in the case of angiogenesis where despite the observed decrease in ANGPT1 levels in MIBC in comparison to NMIBC, the tumour is apparently at an increased aggressive state." (PMID 27683119, 2016). "Further studies have revealed that glipizide suppresses tumor-induced angiogenesis through down-regulating HMGIY/ANGPT1 signals, but not tumor cell proliferation, thereby inhibiting PC tumor growth and metastasis." (PMID 27292155, 2016). "In a previous study into the role of angiopoietin-1 and -2 in the RIP1-Tag2 model, increased tumor vascular perfusion was positively correlated to an increase in proliferation of tumor cells and an enlarged tumor volume." (PMID 25978773, 2015).
tumor (continued). "The ANGPT1/ ANGPT2 transcription ratio was found decreased in larger tumours and especially in tumours without lymphatic spread." (PMID 26044849, 2015). "Those genes showing high expression in CXXC5HIGH primary human AML cells and being significantly altered (i.e. increased) after CXXC5 knockdown included one potential tumor suppressor (TSC22), the cytokine Angiopoietin 1, a selenium transport protein and the hematopoietic growth factor receptor KIT." (PMID 25605239, 2015). "In conclusion, the analysis of patient data led us to the suggestion that the progressive lack of ANGPT1 from G1 to G3 tumours comes with reduced vessel ripening which is marked immunohistochemically by weak CD31 staining." (PMID 26044849, 2015). "Therefore, an increased expression of ANGPT1 and ANGPT2 in tumour tissue hints to an escalation of tumour malignancy on the grounds of an altered vascularisation." (PMID 26044849, 2015). "Mast cells can exert pro-tumorigenic effects by secreting factors like VEGF, angiopoietin-1, CXCL1, and IL-8 that promote tumor angiogenesis, as well as growth factors such as PDGF, NGF, SCF, FGF2, and proteases that facilitate tumor cell growth and metastases." (PMID 24455486, 2014). "In addition to VEGF and its receptors, angiopoietin 1 and 2 (ANG-1 and ANG-2) and their tyrosine kinase receptor Tie-2 have been identified as major players in the processes of growth and remodelling of tumor vasculature." (PMID 20652008, 2010). "In addition, there are angiogenesis‐related markers, including ANGPT1, CD40LG, HIF1A, CCL5, and GPR87, which could contribute to tumour vascularisation." (PMID 40754672, 2025). "The target genes of Runx2—vascular endothelial growth factor (VEGF), angiopoietin-1 (Ang-1), BSP, OPN, and matrix metalloproteinases (MMPs)—promote the differentiation, migration, and invasion of endothelial cells during angiogenesis, which is crucial for tumor growth and metastasis." (PMID 39595568, 2024). "Moreover, it secreted VEGF, ANGPT1, and FGF-2 to facilitate angiogenesis and tumor invasion." (PMID 38041687, 2024). "Ex vivo analysis of tumor vasculature confirmed the in vivo imaging results qualitatively: While H&E staining showed intratumoral hemorrhage in untreated tumors, angiopoietin-1 treated tumors exhibited almost no intratumoral hemorrhage and the expression of CD31 was reduced." (PMID 37221619, 2023). "During numerous investigations regarding tumor progression, expression levels of pro-angiogenic regulators, such as vascular endothelial growth factor-A (VEGF-A), basic fibroblast growth factor (bFGF), and angiopoietin 1 and 2 (Ang1, Ang2), are usually increased." (PMID 36829966, 2023). "Contrastingly, basophils may exert pro-tumor activities, through release of pro-angiogenic and lymphangiogenic mediators, such as VEGF-A and VEGF-B, CXCL8, angiopoietin-1, hepatocyte growth factor, and tryptase, and may suppress anti-tumoral immune responses, such as through T-reg interactions." (PMID 32645919, 2020). "Alternatively, these DCs could modulate the tumor microenvironment by secreting vasculogenic factors such as vascular endothelial growth factor D (VEGF-D), platelet-derived growth factor C (PDGFC), and angiopoietin 1 (ANGPT1)." (PMID 31731454, 2019). "Even though both mesothelioma cell lines express the Angiopoietin-1/-2 and Tie-2, murine Tek-deltaFc hampered AB1 but not AE17 mesothelioma growth in vivo by enhancing tumor cell apoptosis and limiting tumor angiogenesis." (PMID 29774102, 2018). "The eight probes extracted from the RFECV method showing discriminative power between tumour and nontumour samples included cg17105014 (GYPC), cg23273897 (MME), cg22083047 (PRICKLE2), cg09396217 (ANGPT1), cg01049530 (BMP3), cg18237405 (CPNE5), cg12741420 (IRF4) and cg11754206 (KCNB2)." (PMID 36779430, 2023).
tumor (continued). "In contrast, under the simultaneous stimulation of Angpt1/2 + Neamine, no significant change was found in these indexes, further indicating that the influence of SHP-2 on the migration and invasion abilities of TEMs and tumor micro-angiogenesis is mediated by the PI3K/Akt/mTOR signaling pathway." (PMID 37304233, 2023).
cancer (51 papers, 2002 to 2025). A tumor composed of atypical neoplastic, often pleomorphic cells that invade other tissues. "The GWAS results suggested that carriers of minor alleles of the rs1283671 and rs1283720 SNPs within the ANGPT1 gene region were less sensitive to opioid analgesics and thus required greater amounts of daily opioid analgesics in cancer pain treatment." (PMID 36230616, 2022). "Two pro-cancer cytokines M-CSF and Angiopoietin-1 are remarkably decreased with combinational treatment." (PMID 40145650, 2025). "While Angpt1 counteracts hyperpermeability, Angiopoietin 2 (Angpt2) is upregulated in human cancer and its activation weakens the vascular barrier." (PMID 38426110, 2024). "Increased ANGPT2/ANGPT1 ratio at the mRNA level has been reported to correlate with neo‐angiogenesis and poor prognosis in many cancer types." (PMID 35266635, 2022). "In conclusion, our GWASs discovered SNPs and a gene that were associated with opioid analgesic requirements in the treatment of cancer pain, including the ANGPT1 rs1283671 and rs1283720 SNPs and SLC2A14 gene." (PMID 36230616, 2022). "In a colorectal cancer model, IL6 and angiopoietin 1 secreted by MSCs provoked cancer cells to produce endothelin 1, resulting in the promotion of cancer angiogenesis." (PMID 35629138, 2022). "We chose these peptides because these genes, such as Annexin 2, Calprotectin A8, Calprotectin A9, Keratin 19, Keratin 8, Angiopoietin-1, Tissue inhibitor of metalloproteinase (TIMP), and Afamin, are associated with cancer progression." (PMID 36672532, 2022). "Angiopoietin-1 (Ang-1) stimulates vessel stabilization and maturation, while its role in the development of cancer remains rather vague." (PMID 34833409, 2021). "On the other hand, Angiopoietin-2 acts as an inhibitor of the Angiopoietin-1/Tie2 signaling pathways, thus facilitating the destabilization of quiescent endothelium in cases of inflammation and cancer." (PMID 34833409, 2021). "ANGPT2 encodes for the angiopoietin-2 protein, which competitively inhibits angiopoietin-1 by specifically binding to the angiopoietin receptor, and thereby modulates the growth and progression of several cancers." (PMID 32644941, 2020). "iii.Expression of both receptor and ligand genes is decreased in cancer, such as ANGPT1-TEK, CCL21-CCBP2, CCL14-CCBP2, L1CAM-CNTN1 and NCAM1-GFRA1." (PMID 28821810, 2017). "The rates of both cancer cell proliferation and apoptosis decreased significantly in the presence of angiopoietin-1." (PMID 11870550, 2002). "However, to date, there has been no study reporting an association of ANGPT1 SNPs with the risk and clinical outcome of cancers." (PMID 22496856, 2012). "AMG-386 is a small peptibody against the TIE2 ligands ANGPT1 and ANGPT2, and its efficacy is currently tested against different types of cancer, including BCa, in phase 1 and 2, clinical trials (NCT00511459, NCT00807859, and NCT01042379)." (PMID 32260072, 2020). "ANGPT1 is an established drug target for the treatment of cancer, but we did not identify any evidence of drug development related to IHD." (PMID 37940228, 2023). "In addition, Angiopoietin-1 in angiogenesis and tissue inhibitor of metalloproteinase (TIMP, endogenous inhibitors of matrix metalloproteinases) were also reported with cancer aggressiveness." (PMID 36672532, 2022). "Cannabigerol-specific effects included the inhibition of angiopoietin-1, MMP3 and VCAM-1, indicating that its anti-cancer effects may be mediated by the modulation of vascular-immune interactions." (PMID 36923728, 2022). "Subgroup analyses showed the baseline level of plasma angiopoietin-1 was median 736.6 pg/mL (IQR 496.5–1177.7, range 303.7–1839.7) in stage III and IV cancer and 1299.0 pg/mL (IQR 1224.2–1844.0, range 402.4–2400.7) in stage I and II cancer (Mann-Whitney U test, p = 0.1439)." (PMID 32799882, 2020).
cancer (continued). "Proangiogenic plasma alterations such as Angiopoietin-1 (Ang1), VEGF and soluble VEGFR1 may result in cancer patients developing recurrent disease after surgery." (PMID 25329517, 2014). "Although the present results need to be corroborated by more research with larger sample sizes, these findings indicate that these SNPs in the ANGPT1 and SLC2A14 genes could serve as markers that predict the efficacy of opioid analgesics in the treatment of cancer pain." (PMID 36230616, 2022). "The genes which have been reported to involve the cancer cell invasion (ENPP2, ADCY8), dysregulated cellular metabolism (CYC1), and angiogenesis (ANGPT1), immune inhibition (ANXA3) amplified notably in the high-risk group, which might elaborate the aggressiveness and malignancy in this group." (PMID 34568069, 2021). "Angiopoietin-1 (Ang1), a strong activator of intracellular PI 3′-kinase/Akt, was also demonstrated that it may be useful as an inhibitor of TNF-α-induced inflammation and cancer progression." (PMID 27713121, 2016). "Intriguingly, in some cases, the expression levels of ANGPT1 and TGFBR2 did not correlated with miR-204 levels as is common when compare tissues and cell lines because the heterogeneity of cancer cells." (PMID 27703260, 2016).
infection (11 papers, 2010 to 2025). The state of being infected such as from the introduction of a foreign agent such as serum, vaccine, antigenic substance or organism. "As an antagonistic gene of Angpt1, the mRNA level of Angpt2 was significantly down-regulated at 10–12 weeks post-infection, indicating elevated angiogenesis." (PMID 41334166, 2025). "qRT-PCR analysis also showed that the angiogenesis-related genes, Angpt1, Id1, and Lyve1, were significantly upregulated at 10 weeks post-infection, and Pecam1 was significantly upregulated at 10–12 weeks post-infection." (PMID 41334166, 2025). "Beyond CXCL5, our machine-learning approach highlighted several other novel candidates: PDGF-B, Galectin-1, CXCL11, ANGPT1, EGF, TIE2, MCP-2, and NOS3 that each outperformed CXCL5 in discriminating a dormant infection from uninfected joint replacements." (PMID 41387890, 2025). "One re-implantation originally labeled indeterminate by clustering was reevaluated against the nine-marker panel and expressed eight of nine dormant-infection proteins (89%, PDGF-B, Gal-1, CXCL11, ANGPT1, EGF, TIE2, MCP-2, and NOS3) prompting its reassignment as a dormant infection." (PMID 41387890, 2025). "A nine-analyte synovial panel consisting of PDGF-B, CXCL5, CXCL11, MCP-2 (CCL8), ANGPT1, TIE2, EGF, NOS3, and Gal-1 distinguished dormant infection from truly aseptic cases with 100% specificity and positive predictive value (sensitivity 22%, negative predictive value 74%)." (PMID 41387890, 2025). "Notably, direct infection of HMVEC-Ls induced the upregulation of VEGFA, ANGPT1 (angiopoietin-1), and FGF2 gene expression, as well as upregulation of VEGF receptor genes FLT1, KDR, and NRP1." (PMID 37773065, 2023).
retinopathy (5 papers, 2013 to 2023). "Interestingly, intravitreal administration of angiopoietin-1 was shown to prevent vascular degeneration in mouse models of retinopathies." (PMID 34971428, 2021). "Angpt1 protein is a critical actor involved in vessel maturation since it mediates migration, adhesion and survival of endothelial cells, whereas Efnb2 protein is involved in angio-proliferative retinopathy." (PMID 24963632, 2014). "Although the VEGFR pathway is described as being central to the progression of retinal disorders, the TIE2 receptor pathway (the target for angiopoietin-2 [ANG2] and angiopoietin-1 [ANG1]) constitutes another component of the vascular development system." (PMID 37191621, 2023).
adenocarcinoma (3 papers, 2009 to 2023). A common cancer characterized by the presence of malignant glandular cells. "Note, in the context of angiogenesis we found angiopoietin 1 (Angpt1) and tyrosine kinase with immunoglobulin and epidermal growth factor homology domains (TIE1) also down regulated in adenocarcinoma." (PMID 19812696, 2009).
cardiovascular disease (3 papers, 2016 to 2024). "Genetically predicted levels of LRP12, prothrombin, angiopoietin-1 (ANGPT1), and low-density lipoprotein receptor–related protein 4 (LRP4) were positively associated with VTE and 3 cardiovascular diseases." (PMID 38029854, 2024). "The information of Angpt1 in subclinical cardiovascular disease is limited." (PMID 27991547, 2016).
bacterial infection (2 papers, 2010 to 2022). "Increased levels of PDGFs and angiopoietin-1 were associated with a favourable outcome in children with severe bacterial infection." (PMID 35660785, 2022).
infectious disease (2 papers, 2014 to 2022). A disorder directly resulting from the presence and activity of a microbial, viral, or parasitic agent in humans. "Vascular endothelium activation and dysfunction are linked with the production of several biomarkers such as angiopoietin-1 (Ang-1) and angiopoietin-2 (Ang-2) in infectious diseases." (PMID 35735506, 2022).
brain disorder (1 paper, 2025). A disease affecting the brain or part of the brain. "In addition, the UFAG, ANGPT1, serves as a convergent downstream target of multiple risk transcription factors implicated in distinct brain disorders." (PMID 41001519, 2025).
hematological cancers (1 paper, 2024). "Particularly controversial is the increased concentration of various growth factors, such as PDGF, EGF, VEGF and Angiopoietin-1, whose role in the pathogenesis of hematological cancers is clearly negative." (PMID 38673624, 2024).
neurodegenerative disease (1 paper, 2022). A disorder of the central nervous system characterized by gradual and progressive loss of neural tissue and neurologic function. "This is illustrated by the association of APP to both neurogenesis and neurodegenerative diseases as well as the correlation of ANGPT1 with both ROP and diabetic retinopathy." (PMID 33895781, 2022).
ANGPT1 also shares sentences with these, for which no sentence is quoted: heart failure (3 papers); pulmonary hypertension (3); acute kidney injury (2); acute myocardial infarction (2); Arthritis (2); brain tumor (2); cognitive decline (2); depression (2); infertile (2); juvenile idiopathic arthritis (2); non-proliferative diabetic retinopathy (2); ocular hypertension (2); portopulmonary hypertension (2); primary open-angle glaucoma (2); septic shock (2); systemic inflammatory response syndrome (2); thyroid cancer (2); acute liver failure (1); acute lymphoblastic leukemia (1); acute megakaryoblastic leukemia (1); acute-on-chronic liver failure (1); adrenocortical tumor (1); age-related macular degeneration (1); AIDS (1); amyotrophic lateral sclerosis (1); Anxiety (1); arterial embolism (1); Behçet disease (1); benign prostatic hyperplasia (1); bone metastasis (1).
A further 62 diseases each share a sentence with ANGPT1 in 1 paper.